CASP1 (caspase 1)
Diseases named in the same sentence as CASP1 in open-access papers (continued):
Sharing a sentence is not in itself a finding about the gene and the disease.
periodontitis (continued). "It suggested that caspase-1 and pyroptosis is important in producing and releasing IL-1β in periodontitis." (PMID 29184853, 2017). "Some studies have provided clues that inflammasome and caspase-1 be involved in the initiation and progression of periodontitis." (PMID 29184853, 2017). "In this study, we examined the expressions of NLRP3, cleaved-caspase-1 (active), and IL-1β expression, each of which were upregulated in human periodontitis gingival tissue, compared to health gingiva." (PMID 29184853, 2017). "The aim of this study is to investigate the effect of hypoxia on caspase-1 activation, IL-1β maturation, and a possible mechanism of hypoxia formation during periodontitis." (PMID 29184853, 2017). "In periodontitis, the periodontopathic pathogen, A. actinomycetemcomitans, has been involved in caspase-1 activation and secretion of IL-1β and IL-18 in the monocytes/macrophages." (PMID 29184853, 2017). "In periodontitis, hypoxia is a propelling factor of P. gingivalis LPS in activating caspase-1 cascade." (PMID 29184853, 2017). "Spearman's correlation analysis was conducted to examine the relationships between variables.In saliva samples, NLRP3, caspase-1, IL-1β, and IL-18 were the highest in the periodontitis group (p < 0.005), while IL-37 was highest in the healthy group (p < 0.005)." (PMID 40267956, 2025). "Understanding the specific contributions of caspase-1 and caspase-4 in periodontitis pathogenesis could pave the way for novel therapeutic interventions aimed at restoring immune homeostasis and preventing disease progression." (PMID 40137780, 2025). "Thus, further research into caspase-1 activity in periodontitis is required, particularly at the molecular level." (PMID 36794778, 2023). "Thus, it is suggested that future research measure the level of TNF-α and caspase-1 relative to the severity of periodontitis." (PMID 36794778, 2023). "Caspase-1/4/5/11/3/8 levels have all been reported to be increased in periodontitis." (PMID 36093182, 2022). "More recently, RIPK1, RIPK3, and MLKL have been identified to be involved in the mediation of the activation of NLRP3/caspase 1, which might contribute to the activation of pyroptosis during periodontitis." (PMID 36093182, 2022). "In our study, the expression of inflammatory cytokines in OSCC showed that periodontitis-associated bacteria significantly (p < 0.05) upregulated IL-6, TNF-α, IL-18, ASC (up to six times), and caspase-1 (up to four times) but downregulated NF-κB, NLRP3, and IL-1β (less than 0.5 times)." (PMID 34660289, 2021). "Similarly, we found the staining of IL-1β, ASC, and Caspase-1 was also significantly stronger in periodontitis group." (PMID 32903638, 2020). "Furthermore, we found that the phosphorylation of NF-κB p65 and the expression of NLRP3, ASC and caspase-1 were increased in the gingival epithelium in periodontitis, while they were decreased upon VD3 treatment." (PMID 31691738, 2019). "Our study verified that NLRP3, cleaved-caspase-1 and IL-1β were enhanced in periodontitis tissues." (PMID 29184853, 2017). "It is therefore reasonable to consider caspase-1 be involved in the pathogenesis of periodontitis." (PMID 29184853, 2017). "In addition, ZBP1 can form a ZBP1-NLRP3 inflammasome complex to mediate caspase-1 activation and IL-1β maturation, suggesting that inflammatory vesicle signalling and PANoptosis may co-exist in the pathological process of periodontitis." (PMID 40612110, 2025). "Furthermore, rank-sum test analysis in this study revealed differential expression of key PANoptosome components such as RIPK3, CASP8, and CASP1, suggesting that periodontitis may involve ZBP1-mediated PANoptosome formation." (PMID 40612110, 2025).
periodontitis (continued). "Additionally, in inflammatory environments like periodontitis, it was shown that the expression of NLRP3 inflammasome components is enhanced in response to deficient SOD2 activity, while caspase-1-IL-1β axis is also magnified, suggesting that SOD2 plays a protective role under inflammatory stimuli." (PMID 39329909, 2024). "Furthermore, the results of this study confirmed the interactive relationship between TNF-α and caspase-1 salivary levels, which may play a considerable role in triggering the processes that lead to chronic inflammation in clinical periodontitis." (PMID 36794778, 2023). "Similarly, VX765, a caspase-1 inhibitor, reduced the expressions of IL-1β, in PDLCs stimulated with E. coli LPS or P. gingivalis LPS, and decreased the inflammatory responses during periodontitis in vivo." (PMID 35008798, 2021). "Salivary exosomal miR-223-3p is significantly downregulated in periodontitis and plays a key role in suppressing pyroptosis, a programmed cell death process, in macrophages by targeting the NLRP3-caspase-1-GSDMD signaling axis." (PMID 41322905, 2025). "In a recent study, patients with chronic hepatitis C and periodontitis were found with significantly more elevated levels of NLRP3, caspase-1, and IL-18 in GCF samples, than systemic healthy patients with periodontitis." (PMID 38817019, 2024). "AZGP1 participates in the pathogenesis of periodontitis by aggravating macrophage M1 polarization and pyroptosis through the NLRP3/caspase-1 pathway.signaling pathway." (PMID 38800469, 2024). "The aim of this study was to evaluate the salivary levels of caspase-1 and TNF-α and determine their accuracy in differentiating periodontitis patients from individuals with a healthy periodontium." (PMID 36794778, 2023). "Caspase-1 and TNF-α salivary levels were increased in periodontitis patients compared to the healthy controls, and were positively correlated with clinical parameters." (PMID 36794778, 2023). "Based on the results of the ROC curve, which was used for differentiating periodontal health from periodontitis, the results of AUC for TNF-α and caspase-1 were 0.978 and 0.998, respectively." (PMID 36794778, 2023). "For differentiating periodontal health and periodontitis, the area under the curve (AUC) values of TNF-α and caspase-1 were 0.978 and 0.998, while the proposed cut-off points were 128.163 pg/ml and 1.626 ng/ml, respectively." (PMID 36794778, 2023). "Studies restricted their focus on caspase-1/GSDMD, the role of caspases, GSDMs, granzymes, and ELANE, which, beyond caspase-1/GSDMD, remain to be fully elucidated in periodontitis." (PMID 36093182, 2022). "We recently found that the levels of IL-1β and inflammasome components increased in periodontitis patients and P. gingivalis induced IL-1β release via TLR2/TLR4-NLRP3/AIM2 inflammasome-caspase-1 pathway activation." (PMID 27386246, 2016). "Furthermore, caspase-1 and TNF-α showed high sensitivity and specificity in the diagnosis of periodontitis, as well as distinguishing periodontitis from periodontal health." (PMID 36794778, 2023). "Limited evidence in periodontitis revealed that P. gingivalis, Mycoplasma salivarium, Treponema denticola surface protein Td92, E. faecalis, and LPS can induce pyroptosis in macrophages through the NLRP3/caspase-1/GSDMD pathway, contributing to the pathogenesis and development of periodontitis." (PMID 36093182, 2022). "However, hypoxia appeared in periodontitis, in which NLRP3, cleaved-caspase-1, interleukin 1 beta (IL-1β) and caspase-1-induced cell death was enhanced in periodontitis specimens." (PMID 29184853, 2017). "Additionally, salivary levels of NLRP3, ASC, and IL-1β were higher in chronic or aggressive periodontitis patients than in healthy patients; however, levels of caspase-1 were not altered." (PMID 41440367, 2025).
periodontitis (continued). "Thus, selected salivary biomarkers showed high sensitivity and specificity in the diagnosis of periodontitis and distinguishing it from periodontal health at the proposed cut-off points (128.163 pg/ml of proinflammatory cytokines [TNF-α] and 1.626 ng/ml of caspase-1)." (PMID 36794778, 2023). "No research has looked into the relationship between caspase-1 and TNF-α levels and periodontitis up until this point." (PMID 36794778, 2023). "Both groups of periodontitis patients (CHC + P and P) expressed significantly elevated levels for all of the three assessed proinflammatory mediators (NLRP3, CASP1, and IL-18) as compared to the nonperiodontitis groups (CHC and H)." (PMID 34840527, 2021). "Interestingly, when researchers looked at gingival tissues rather than saliva, they found higher expression of caspase-1, NLRP3, ASC and AIM2 in patients with chronic periodontitis." (PMID 41440367, 2025).
leukemia (24 papers, 2004 to 2026). A malignant (clonal) hematologic disorder, involving hematopoietic stem cells and characterized by the presence of primitive or atypical myeloid or lymphoid cells in the bone marrow and the blood. "In addition, activation of the NLRP3 inflammasome causes glucocorticoid resistance in leukemia cells by cleavage of the glucocorticoid receptor and decreased promoter methylation of caspase-1 and NLRP3." (PMID 30937316, 2019). "Inspired by a recent article showing that steroid-resistance in leukemia cells is caused by caspase-1-dependent cleavage of the GR30, we hypothesized that the activation of the NLRP3 inflammasome in THP-1 cells could lead to a reduction of GR levels." (PMID 27883019, 2016). "Increased caspase-1 levels have been linked to glucocorticoid resistance in leukemia cells." (PMID 27190722, 2016). "With regards to CASP‐1, all leukemia subtypes exhibited high CASP1 expression in comparison to other cancer types except alveolar soft part sarcoma." (PMID 40104043, 2025). "The comparison revealed consistent trends, with BCP‐ALL and MLL‐ALL bearing the highest NLRP3 expression, T‐ALL exhibiting the lowest IL‐1β expression and a persistent increase in CASP1 expression across the leukemia panel." (PMID 40104043, 2025). "Together, the results demonstrated that ATRA+MRT treatment can activate the AIM2 inflammasome-caspase-1 pathway to inhibit p21 proteasomal degradation, promoting myeloid differentiation and cell growth arrest in leukemia cells." (PMID 38466568, 2024). "In this study, we found that curcumin induced the expression of NLRC4, AIM2, and IFI16 inflammasomes by upregulated ISG3 transcription factor complex in leukemia cell U937, which activates caspase 1 and promotes cleavage of GSDMD." (PMID 35435150, 2022). "Thus, the expression of CASP1 may be a promising diagnostic indicator for leukemia." (PMID 33999861, 2021). "We discovered that mRNA expression levels of CASP1 are increased in leukemia cell lines, especially in acute myelocytic leukemia (AML)." (PMID 33999861, 2021). "We inquired the CCLE database to analyse the CASP1 expression in multiple cell lines and discovered a higher transcriptional expression of CASP1 in leukemia cell lines compared to other cancer types." (PMID 33999861, 2021). "We applied AML leukemia cells with NF-κB inhibitor Bay11-7082, and found that Bay11-7082 significantly decreased the protein levels of LPS+ATP induced pNF-κB, pro-caspase-1, pro-IL-1β, cleaved caspase-1 and cleaved IL-1β (right column 1 and 3)." (PMID 34211462, 2021). "Using the Oncomine dataset, we discovered that CASP1 ranked in the top 15% based on mRNA expression levels in the Coustain-Smith Leukemia and Haslinger Leukemia datasets." (PMID 33999861, 2021). "Here, we demonstrated that NF-κB inhibitor Bay11-7082 decreased the secretion of IL-1β and IL-18 from leukemia cells and down-regulated the protein expression of pNF-κB, pro-caspase-1, pro-IL-1β, active caspase-1 and IL-1β." (PMID 34211462, 2021). "We used sequencing data from multiple cancer gene databases to analyze the gene expression and regulatory network of CASP1 in leukemia." (PMID 33999861, 2021). "They found increased expression of key components of the NALP3 pathway - CASP1 (encoding caspase 1) and its activator NLRP3 in GC-resistant leukemia cells compared to GC-sensitive leukemia cells." (PMID 33747919, 2021). "In the present study, a detailed analysis of cancer versus normal samples was performed to explore the relationship between CASP1 and leukemia." (PMID 33999861, 2021). "These secondary metabolites inhibit the signal transduction enzymes caspase-1 and caspase-3 and mitigate the production of interleukin 1- β in a leukemia cell line." (PMID 30643697, 2019). "Caspase-1 level is a marker for glucocorticoid (e.g., prednisolone) resistance in leukemia cells; indeed, we observed an upregulation of caspase-1 expression in primary ATL patient cells after recurrence." (PMID 27190722, 2016).
leukemia (continued). "Mechanistically, blocking autophagic clearance resulted in the accumulation of cytosolic dsDNA fragments, activating the AIM2 inflammasome-caspase-1 pathway and consequently inhibiting p21 proteasomal degradation, which promoted myeloid differentiation and cell growth arrest in leukemia cells." (PMID 38466568, 2024). "Although the role of CASP1 in carcinogenesis is controversial, it may be a prospective indicator for leukemia prevention and treatment." (PMID 33999861, 2021). "Furthermore, overexpression of CASP1 was strongly related to poor survival in multiple leukemia cohorts." (PMID 33999861, 2021). "In summary, CASP1 has widespread impact on immune response in leukemia." (PMID 33999861, 2021). "The mRNA of CASP1 was also overexpressed in leukemia cell lines, analyzed by CCLE." (PMID 33999861, 2021). "Our study indicated that E2F1 may be a crucial factor of CASP1 in regulating the proliferation of leukemia cells, and was consistent with previous reports." (PMID 33999861, 2021). "Therefore, we speculated that CASP1 was highly expressed in most leukemia patients, especially in patients with poor prognosis." (PMID 33999861, 2021). "Interestingly, the comparison of NLRP3 and Caspase 1 expression between glucocorticoid sensitive and resistant primary leukemia cells isolated from 444 patients shows that high expression of Caspase 1 and NLRP3 is associated with an increase in glucocorticoid resistance." (PMID 33716981, 2021). "As for malignancies of lymphoid origin, CASP1 and NLRP3 showed significantly higher expression in glucocorticoid-resistant primary leukemia cells from patients diagnosed with acute lymphoblastic (ALL) compared to cells sensitive to glucocorticoids." (PMID 38397043, 2024). "As caspase-1 is pivotal for the activation of NLRP3 inflammasome, we treated primary AML leukemia cells with caspase-1 inhibitor Z-YVAD-FMK." (PMID 34211462, 2021). "Meanwhile, CASP1 and its activator NLRP3 are the core component of the inflammasome, and its overexpression in leukemia leads to glucocorticoid resistance." (PMID 33999861, 2021). "In contrast, leukaemia cell lines (CCRF-CEM and KG-1a) probably activate caspase-1 through different inflammasome complexes." (PMID 35082671, 2021). "Our results showed that caspase-1 inhibitor Z-YVAD-FMK down-regulated IL-1β and IL-18 secretion, suppressed proliferation and enhanced apoptosis of primary leukemia cells." (PMID 34211462, 2021). "The activation of NLRP3 inflammasome in AML cells promotes leukemia cells proliferation, inhibits apoptosis and increases resistance to chemotherapy, while inactivation of NLRP3 by caspase-1 or NF-κB inhibitor shows leukemia-suppressing effects." (PMID 34211462, 2021). "Caspase-1 (CASP1) is best known for regulating IL-1β processing and pyroptosis; however, its role in leukemia has not been clearly defined." (PMID 41500224, 2026). "For example, glucocorticoid‐resistant leukemia cells were found to overexpress NLRP3 and CASP1, suggesting that targeting NLRP3‐signaling pathways could improve response rates, particularly in treatment‐resistant diseases." (PMID 40104043, 2025). "In this study, we demonstrated that curcumin induced the expression of AIM2, IFI16, and NLRC4 inflammasomes in leukemia cells U937 by increasing the expression levels of ISG3 transcription factor complex, which activated caspase 1, promoted cleavage of GSDMD, and induced pyroptosis." (PMID 35435150, 2022). "We discovered that CASP1 is primarily related to LYN kinase and LCK kinase in leukemia." (PMID 33999861, 2021). "We discovered that mRNA expression levels of CASP1 in patients with leukemia were upregulated compared with normal samples." (PMID 33999861, 2021). "Thus, we sought to assess the expression profiles of NLRP3, CASP1, and IL‐1β in pediatric blood cancer samples, reasoning that the largest therapeutic impact of NLRP3 inhibition on cancer progression likely occurs in leukemia subtypes with the highest expression levels." (PMID 40104043, 2025).
leukemia (continued). "If ASC is required for GvHD by enhancing the function of pathogenic T cells, then therapeutically targeting the inflammasome receptor and/or caspase-1 may specifically eliminate the alloreactive T cell pool to improve GvHD outcomes without influencing Graft-versus-leukemia responses." (PMID 37749127, 2023). "Oncogenes (YAP1, Survivin) were shown to be repressed and TSGs (p21, PTEN, CASP1) upregulated under IRF8 overexpression in renal cancer, and negative feedback occurred between IRF8 and β-catenin in leukemia." (PMID 28388578, 2017).